GSK3B (glycogen synthase kinase 3 beta)
Diseases named in the same sentence as GSK3B in open-access papers (continued):
Sharing a sentence is not in itself a finding about the gene and the disease.
cervical carcinoma (44 papers, 2010 to 2024). A carcinoma arising from either the exocervical squamous epithelium or the endocervical glandular epithelium. "The preceding findings suggested that GSK3B was implicated in cervical cancer tumorigenesis and that the prognosis was poorer for patients with high GSK3B levels." (PMID 39166606, 2024). "Online bioinformatic tools were used to conduct the pre-investigation of linc00958/miR-185-5p/RSF-1 and predict the associations between RSF-1 and AKT1/GSK3β/VEGFA in cervical cancer." (PMID 36056431, 2022). "STYK1 was previously shown to cause GSK-3β (Ser9) phosphorylation via activating AKT phosphorylation at the Thr308 residue in cervical cancer Hela cell." (PMID 27628214, 2016). "This is the first study to investigate the relationship between high-risk HPV and GSK3β in cervical cancer." (PMID 26560046, 2015). "We found significant downregulation of PMS2 in cervical carcinoma, which was negatively associated with phosphorylated GSK-3β (s9)." (PMID 20178594, 2010). "Our results suggested that the downregulation of PMS2 in cervical carcinoma tissues might be associated with pGSK-3β production and GSK-3β inactivation." (PMID 20178594, 2010). "This study aimed to investigate whether GSK3β is a target of high risk HPV in cervical cancer." (PMID 26560046, 2015). "sGCβ1 impacted signaling in endometrial and cervical cancer cells through significant downregulation of Akt pathway affecting some of its main targets such as GSK-3β and c-Raf." (PMID 38205317, 2024). "The present study silenced GSK3B with siRNAs and/or chemical inhibitors to determine its role in HeLa cervical cancer cell proliferation and migration as well as in xenograft tumor growth." (PMID 39166606, 2024). "We knocked down GSK3B in HeLa cells and performed transcriptomic sequencing on them to elucidate the mechanisms by which GSK3B drives cervical cancer progression." (PMID 39166606, 2024). "In the present work, we knocked down GSK3B and/or chemically inhibited it in HeLa cells and in xenograft tumors to clarify its functions in cervical cancer." (PMID 39166606, 2024). "Public databases and clinical specimens showed that GSK3B was upregulated in cervical cancer tissues and correlated with poor prognosis." (PMID 39166606, 2024). "To further investigate the oncogenic role of GSK3B in cervical cancer, we performed an in vivo experiment in nude mice." (PMID 39166606, 2024). "Our data suggested that GSK3B regulated cervical cancer cell proliferation and migration by modulating the PI3K/Akt signaling pathway and epithelial-to-mesenchymal transition (EMT)." (PMID 39166606, 2024). "linc00958/miR-185-5p/RSF-1 modulates cisplatin resistance and angiogenesis through AKT1/GSK3β/VEGFA pathway in cervical cancer." (PMID 36056431, 2022). "TRPM4 silencing was reported to promote GSK-3β-dependent degradation of β-catenin and reduce β-catenin/Tcf/Lef-dependent transcription to inhibit cervical cancer." (PMID 36072430, 2022). "Together, SCD1 was negatively regulated by KLF9 and it activated the Akt/GSK3β signaling pathway to promote the malignant progression of cervical cancer cells." (PMID 35609330, 2022). "The experimental results in this paper indicate that KLF9/SCD1 expression can regulate the Akt/GSK3β signaling pathway in cervical cancer cells." (PMID 35609330, 2022). "Compared with the negative control group, the protein levels of β-catenin in the APMAP knockdown group decreased and the protein levels of p-GSK3β/GSK3β increased in the three types of cervical cancer cells." (PMID 34539899, 2021). "Recent studies have shown that inhibition of GSK3B and HDACs induces anti-tumor effects in endometrial and cervical cancer." (PMID 32698955, 2020). "Previous studies have reported that silencing DEK inhibits the Wnt/β-catenin signaling pathway by mediating GSK-3β phosphorylation in cervical cancer." (PMID 33232276, 2020).
cervical carcinoma (continued). "To further evaluate the impact of metabolic pathways on metabolic modification in cervical cancer, we determined the mRNA transcription and protein expression of key enzymes related to sugar and lipid metabolism, namely, GSK3β, PKM2 and CPT1A." (PMID 31465717, 2020). "We have previously reported that ACTN4 induces the phosphorylation of Akt and GSK-3β in cervical cancer." (PMID 33363146, 2020). "This suggested that DAX1 functions as the tumor promoter in cervical cancer, and that it is involved in the activation of Wnt/β-catenin pathway through GSK3β." (PMID 29497051, 2018). "Taken together, our findings support the notion that overexpression of DAX1 in cervical cancer allows for aberrant binding to the GSK3β promoter, enhancing transcriptional inhibition of GSK3β, which then inhibits the degradation of β-catenin." (PMID 29497051, 2018). "Taken together, PIK3CA E542K and E545K mutations promote glucose metabolism and proliferation by inducing the AKT/GSK3β/β-catenin in cervical cancer cells." (PMID 30547809, 2018). "In terms of the obtained results, the hub proteins KAT2B, PARP1, CDK1, GSK3B, WNK1, and CRYAB have been associated with several cancers in previous studies, but their association with cervical cancer is proposed here for the first time." (PMID 30020984, 2018). "Our data demonstrated that DAX1 is overexpressed in cervical cancer, and that it promotes cell growth and tumorigenicity through activating Wnt/β-catenin pathway mediated by GSK3β." (PMID 29497051, 2018). "In the present study, we found that the expression level of AKT1, p-AKT1 (Ser473), and p-GSK3β (Ser389) were decreased in cervical cancer cells treated with Bufalin, but the expression of GSK3β was increased." (PMID 26758421, 2016). "The proliferation, invading, and colony-forming abilities of cervical cancer cells were associated with HPV16 E6/E7 and GSK3β levels." (PMID 26560046, 2015). "This study investigated how HPV16 regulated GSK3β expression and function to promote cervical cancers." (PMID 26560046, 2015). "The level of GSK3β expression correlated with copy numbers and expression levels of oncogenes of high-risk HPV in cervical cancer cell lines." (PMID 26560046, 2015). "Depletion of Sam68 inhibits migratory and invasive potential of cervical cancer cells as well as the expression of vimentin and fibronectin, possibly through suppressing the Akt/GSK3β/Snail pathways." (PMID 26356073, 2015). "The chronic treatment of EGF in cervical cancer cells has been shown to increase phosphorylation of glycogen synthase kinase-3 (GSK-3β), a regulator of Snail, thus inducing EMT." (PMID 26356073, 2015). "We examined PMS2 and phosphorylated GSK-3β(s9) expression in cervical carcinoma tissues using immunohistochemical staining." (PMID 20178594, 2010). "Moreover, both the database analysis and clinical specimen analysis also showed that GSK3B was upregulated in cervical cancer tissues and high GSK3B expression indicated a poor prognosis." (PMID 39166606, 2024). "Nevertheless, the role of GSK3B in cervical cancer is poorly understood, and it is unknown whether GSK3B inhibitors are efficacious in cervical cancer treatment." (PMID 39166606, 2024). "We also examined the expression of GSK3B in cervical cancer specimens." (PMID 39166606, 2024).
cervical carcinoma (continued). "Therefore, GSK3B suppression reduced cervical cancer cell viability and proliferation by inactivating the PI3K/Akt signaling pathway." (PMID 39166606, 2024). "Further, linc00958/RSF-1 downregulation or miR-185-5p upregulation could alleviate the cisplatin resistance and tube formation in cervical cancer cells via AKT1/GSK3β/VEGFA pathway." (PMID 36056431, 2022). "The finding of the KLF9/SCD1/Akt/GSK3β regulatory axis expands the pathogenesis of cervical cancer." (PMID 35609330, 2022). "Activation of the Akt/GSK-3β/Snail pathway is involved in the occurrence of EMT in cervical cancer." (PMID 34238315, 2021). "Baicalein inhibits cyclin D1 overexpression and arrests the cell cycle at G0/G1 phase through Wnt/β-catenin and protein kinase B/glycogen synthase kinase-3β (AKT/GSK-3β) signaling pathways to suppress proliferation and induce apoptosis of human cervical cancer HeLa and SiHa cells." (PMID 34680171, 2021). "Furthermore, studies from other groups have shown that the ACTN4-Akt axis promotes the degradation of GSK-3β, leading to the stabilization of β-catenin and enhancement of migration and invasion of cervical cancer cells." (PMID 33628783, 2021). "CHN1 can accelerate the occurrence of tumor biological behaviors and may stimulate the activation of EMT through the Akt/GSK-3β/Snail pathway to promote the metastasis of cervical carcinoma." (PMID 34238315, 2021). "Decreased GSK3βtyr216 and increased GSK3βser9 levels have been reported in cervical cancer tissues, which indicates that activated GSK3β may play some roles in the inhibition of tumorigenesis." (PMID 31465717, 2020). "Considering the high activation of AKT/GSK3β/β-catenin in cervical cancer cells with mutant PIK3CA, we inferred that PIK3CA E542K and E545K mutations might promote the nuclear accumulation of β-catenin in cervical cancer cells." (PMID 30547809, 2018). "Our bioinformatics analyses show that miR-106b could promote cervical cancer progression by modulating the expression of GSK3B, VEGFA, and PTK2 genes." (PMID 30275981, 2018). "Of course, further experiments will be required to confirm whether the down-regulation of cyclin D1 by Slug in cervical carcinoma cells also occurs through direct degradation by GSK3β at the protein level." (PMID 27036045, 2016). "Moreover, the expression of signaling molecules of the Wnt/β-catenin signaling pathway, including GSK3β, p-GSK3β, β-catenin, cyclin D1 and c-myc, was detected in the Slug-modified cervical cancer cells and their controls." (PMID 27036045, 2016). "All of the cervical cancer cells subjected to the MK treatment grew much more slowly and expressed less Akt1/p-Akt1, more p21/p27, less p-Rb and fewer molecules (p-GSK3β, β-catenin, c-myc and cyclin D1) of the Wnt/β-catenin signaling pathway than the cells that were not subjected to MK treatment." (PMID 27036045, 2016). "In the present study, we demonstrated that Slug could trans-suppress Akt1/p-Akt1 expression (p < 0.05) in cervical carcinoma cells and then decrease the phosphorylation of GSK3β (p < 0.05) by Akt1." (PMID 27036045, 2016). "LiCl also increased GSK3β transcripts in an HPV16-dependent manner in cervical cancer cells." (PMID 26560046, 2015). "Thus, GSK3B might regulate cervical cancer cell proliferation and survival by modulating the PI3K/Akt signaling pathway." (PMID 39166606, 2024). "Collectively, DD-9 may suppress proliferation and induce apoptosis of liver and cervical cancer cells, possibly at least in part via GSK3-β-mediated crosstalk with the Wnt/β-catenin signaling axis, providing insights into the mechanism for the potency of DD-9 on hepatocellular and cervical cancer." (PMID 38921589, 2024). "Hence, these data confirmed an oncogenic role of GSK3B in cervical cancer." (PMID 39166606, 2024).
cervical carcinoma (continued). "Furthermore, post-transcriptional modifications have been identified in components that negatively regulate the pathway; for instance, in cervical cancer samples, GSK3β is inactivated by the phosphorylation of its Ser9 residue, inducing the over-activation of the Wnt signaling pathway." (PMID 26295406, 2015). "Thus, GSK3B inhibitors may be novel therapeutic modalities against cervical cancer." (PMID 39166606, 2024). "We knocked down GSK3B or inhibited its activity with CP21R7 in HeLa cells to verify its oncogenic role in cervical cancer." (PMID 39166606, 2024). "The expression of seven hub genes in the PI3K/AKT/mTOR pathway were increased in cervical cancer: EIF4EBP1, GSK3B, HRAS, KRAS, NRAS, PIK3CB and PIK3R2." (PMID 36911370, 2023). "Together, the present study indicates that SCD1 is negatively regulated by KLF9 and it activates the Akt/GSK3β signaling pathway to influence the proliferation, migration, invasion, and EMT process of cervical cancer cells." (PMID 35609330, 2022). "The data demonstrated significant downregulation of GSK3β and upregulation of PKM2 and CPT1A in cervical carcinoma and precancerous lesions compared with NCs." (PMID 31465717, 2020). "Some studies also indicated that SC66 effectively inhibited the phosphorylation levels of AKT through disruption of mTOR signaling, and therefore contributes to decrease the expressions of p-GSK-3β and p-FOXO1 in human cervical cancer." (PMID 31168297, 2019). "GSK3β, a highly effective kinase on a substrate (here referred to as β-catenin), was significantly improved, and the p-GSK3β (Ser9) in DAX1-knockdown cervical cancer cells eventually led to the degradation of β-catenin in SiHa and HeLa cells." (PMID 29497051, 2018). "Based on all these results, we propose a novel mechanism by which PA-MSHA suppresses the proliferation and invasion of cervical cancer cells: by activating PTEN and thus inhibiting the AKT/GSK3β pathway." (PMID 27206797, 2016). "Our results thus indicated that GW627368X hindered proliferation and induced apoptosis in cervical cancer cells via the cyclic adenosine monophosphate/PKA/CREB as well as pathway involving EGFR/Ras/MAPK/CRB and Akt/GSK3β/ β-catenin." (PMID 27010855, 2016). "In cervical cancer cells, HPV16 E6/E7 promoted the expression of GSK3β at least in part through transcription." (PMID 26560046, 2015). "The aim of this study was to determine the expression of PMS2 in cervical carcinoma and evaluate the significance of mismatch repair gene PMS2 regulated by glycogen synthase kinase 3β (GSK-3β) in chemosensitivity." (PMID 20178594, 2010). "In line with the results from databases, both the WB analysis and IF analysis showed that GSK3B expression was higher in cervical cancer tissues than in normal paratumor tissues." (PMID 39166606, 2024). "Microarray expression studies of cervical cancer-derived tumors and cell lines have identified the over-expression of genes involved in Wnt pathway maintenance and regulation, such as JUN, MYC, FZD2, RAC1, GSK3β, Dvl-1, and CTNNB1." (PMID 26295406, 2015).
cervical carcinoma (continued). "Our results provide the evidence that stabilization of PMS2 production by GSK-3β was important to improve chemosensitization, indicating the significance of GSK-3β-related PMS2 downregulation in the development of cervical carcinoma and in developing a potential strategy for chemotherapy." (PMID 20178594, 2010). "Our results provide the preliminary evidence that GSK-3β stabilized PMS2 production, which may play an important role in the carcinogenesis and chemotherapy of cervical carcinoma." (PMID 20178594, 2010). "After establishing HOTAIR’s role in modulating key signaling pathways in cervical cancer (CC), we conducted a meta-analysis that revealed elevated levels of PI3K, AKT, HIF1α, and β-catenin proteins in CC tumor samples compared to healthy controls, alongside reduced levels of GSK3β." (PMID 39273054, 2024). "Overall, the results of the present study suggested that GSK3B could promote cell proliferation by activating the PI3K/Akt signaling pathway and promote cell migration by inducing EMT, indicating an oncogenic role of GSK3B in cervical cancer." (PMID 39166606, 2024). "Therefore, we conducted a Western blotting assay and found that DHM inhibited the β-catenin expression and GSK3β phosphorylation in cervical cancer cells while DHM had no obvious influence on Wnt 3 and Wnt 11 expression." (PMID 36499426, 2022). "An inactivated GSK3β could led to increased SNAIL activity and poor prognosis in cervical cancer." (PMID 35230971, 2022). "Furthermore, the KAT2B, PARP1, CDK1, GSK3B, WNK1, and CRYAB, proteins are associated with various cancer types, but their roles in cervical cancer have not been identified." (PMID 30020984, 2018). "However, whether GSK3β plays a role in mediating HPV mediated perturbation of wnt/β-catenin in cervical cancer is not known." (PMID 26560046, 2015).